NFYAP1 (nuclear transcription factor Y subunit alpha pseudogene 1)
Synonyms: formerly NFYAP
Gene: Processed pseudogene on chromosome 13 (63,975,451 to 63,976,422, reverse strand). Ensembl gene ENSG00000237849.
Diseases named in the same sentence as NFYAP1 in open-access papers:
NFYAP1 is named in the same sentence as 2 diseases in open-access papers, as found by Europe PMC text mining. Sharing a sentence is not in itself a finding about the gene and the disease.
NFYAP1 shares sentences with these, for which no sentence is quoted: angle-closure glaucoma (1 paper); cataract (1).